TET2 (tet methylcytosine dioxygenase 2)
Diseases named in the same sentence as TET2 in open-access papers (continued):
Sharing a sentence is not in itself a finding about the gene and the disease.
melanoma (continued). "Accordingly, IDH2 or TET2 reintroduction in melanoma cells restores the 5-hmC landscape, suppresses melanoma growth, and increases tumor-free survival (TFS) in a zebrafish melanoma model." (PMID 31010244, 2019). "TET2 overexpression and the consequent increase in 5hmC levels decrease melanoma cell invasion in murine models." (PMID 30939818, 2019). "HIF-1α knockdown in a metastatic melanoma cell line, is followed by an increase in TET2 gene and protein levels." (PMID 30939818, 2019). "Restoring 5hmC levels by overexpressing TET2 in melanoma cells, TET1 in breast cancer cells, and IDH1 in renal cancer cells demonstrated inhibitory effects in vitro and in vivo." (PMID 30005692, 2018). "Our in vivo experiment showed that the overexpression of TET2 inhibits the growth and metastasis of melanoma." (PMID 27852070, 2017). "Treatment of ascorbate at a physiological level (100 μM) increased the content of 5 hmC in melanoma cell lines derived from different stages toward the level of healthy melanocytes, which was comparable to the effect of overexpressing TET2." (PMID 28623268, 2017). "Overexpressing TET2 partially re-establishes a normal 5 hmC profile in melanoma cells and decreases their invasiveness." (PMID 28623268, 2017). "Ablation of TET2 expression in myeloid cells suppresses the growth of melanoma cells in vivo and induces a switch of the gene expression profile of tumor-associated macrophages from an immunosuppressive to a proinflammatory pattern." (PMID 29156643, 2017). "Published studies have shown that overexpressing TET2 in melanoma cells and TET1 in breast cancer cells increases their 5hmC content and decreases their malignancy in vitro and in vivo." (PMID 25977731, 2015). "Overexpressing TET2 was shown to partially reestablish a normal 5hmC profile in melanoma and decrease invasiveness in rodents." (PMID 25977731, 2015). "Treatment of vitamin C at the physiological level (0.1 mM) promoted the content of 5hmC in melanoma cell lines derived from different stages toward the level of healthy melanocytes, which was comparable to the effect of overexpressing TET2." (PMID 25977731, 2015). "Of the cell lines evaluated, the lowest expression level of both TET1 and TET2 was observed in two metastatic melanoma cell lines." (PMID 25977731, 2015). "Consistent with a previous report, we found that the expression of TET1 and TET2 was consistently decreased in all melanoma cell lines examined, as compared to the normal melanocyte line." (PMID 25977731, 2015). "Significant loss of 5hmC is also a feature of human melanomas, and, interestingly, introduction of active TET2 suppresses melanoma growth." (PMID 24172544, 2013). "Reintroducing active TET2 or IDH2 was found to suppress melanoma growth and increase tumor-free survival in animal models." (PMID 23533770, 2013). "Interestingly, in melanoma Tet2‐mutant CHIP effects seem to act contrary, resulting in reduced tumor burden via a Tet2‐loss mediated onset of proinflammatory tumor‐associated macrophage phenotype that promotes T‐cell infiltration." (PMID 40517440, 2025). "Additionally, the overexpression of TET2 in these melanoma cells effectively reversed the TGF-β1-induced EMT in vitro and inhibited tumor growth in vivo." (PMID 40427015, 2025). "Using single-cell RNA sequencing (scRNA-seq) analysis performed on B16-OVA melanoma tumors, we have shown here that an additional function for TET2 in tumors is to promote expression of certain antigen presentation machinery genes, which is potently enhanced by VC." (PMID 39388288, 2024). "The effect of 5hmC on PRAME expression is likely direct: genome-wide mapping of 5hmC using hydroxymethylated DNA immunoprecipitation sequencing (hMeDIP-seq) reveals significantly increased 5hmC binding at the PRAME 5’ promoter region in TET2-OE cells as compared to control melanoma cells." (PMID 39091741, 2024).
melanoma (continued). "Therefore, we analyzed expression of TET1, -2, and -3 in B16 melanoma and CT-26 tumors and found that TET2 was expressed at the highest level, with TET3 at intermediate levels and TET1 at the lowest level." (PMID 39388288, 2024). "Thus, PRAME expression in melanoma can be negatively controlled by TET2-mediated 5hmC epigenetic modification." (PMID 39091741, 2024). "Taken together, our data uggest that 5hmC loss, likely due to the down-regulation of TET2, plays an important role driving PRAME activation and that this may help drive melanoma malignant transformation and progression." (PMID 39091741, 2024). "This inverse correlation between high TET2 and 5-hmC on the one hand, and low PRAME expression on the other, is consistently observed at a whole-specimen level in melanoma clinical cohorts by IF and IHC for 5hmC, and by RNA-seq for TET2 (based on data in the TCGA and GTEx databases)." (PMID 39091741, 2024). "Similarly, we used violin plots to demonstrate the gene expression levels of components of the TET2/3-STAT1/3-CD274 signaling axis in melanoma cluster (Clusters 0, 1, 2, 3 and 5)." (PMID 36854755, 2023). "Here we investigated the function of TET2 in tumor angiogenesis using melanoma cells (B16F10)." (PMID 36658614, 2023). "Furthermore, reduced mRNA expression of TET2 and TET3 have been implicated in the induction of epithelial-mesenchymal transition in melanoma." (PMID 35372016, 2022). "However, in the B16-OVA melanoma model, TET2 in tumor cells functions as an important mediator of the IFN-γ/JAK/STAT signaling pathway." (PMID 36203205, 2022). "Moreover, TET2 acts as an oncogene in melanoma tumorigenesis by suppressing anti-cancer immune cells." (PMID 33535484, 2021). "In the melanomas, TET2 loss was homogenously diffuse and it was not possible to identify localized areas with loss of TET2 expression." (PMID 34198758, 2021). "Also, TET proteins have been reported to play a crucial role in melanoma, since their ectopic expression of TET2 eradicates tumor proliferation and increases survival in vivo." (PMID 34198989, 2021). "Indeed, the overexpression of TET2 in melanoma cells suppresses tumor initiation and progression by increasing 5hmC levels, and elevated 5hmC by upregulated TET1 recruits the CHOIP-methylosome complex near the genes involved in glioblastomagenesis." (PMID 33926529, 2021). "In melanomas, loss of TET2 was significantly associated with non-bulbar localization (p = 0.0423) and TNM classification (p = 0.0384), but not with other clinicopathological factors." (PMID 34198758, 2021). "The deletion of USP15 in melanoma cells increases TET2 activity." (PMID 33805247, 2021). "In addition, HIF1-α knockdown contributed to enhancing TET2 expression in melanoma and glioblastoma cells, which shed new light on the plausible regulation of expression between these two proteins in malignant cells." (PMID 33352824, 2020). "Overexpression of TET2 in melanoma cells corresponds to higher 5hmC levels." (PMID 32774324, 2020). "Whether Tet2 plays a similar or different role in myeloid cell-mediated tumor growth in cancers other than melanoma awaits further investigation." (PMID 33184433, 2020). "Importantly, the expression of active TET2 or IDH2 into melanoma cells restores the 5-hmC landscape, inhibits melanoma proliferation, and increases survival in animal models." (PMID 29156643, 2017). "Here, in the TGF-β1-induced EMT-like process in melanoma, only TET2 and TET3 are down regulated." (PMID 27852070, 2017). "Within our cohort, MECOM/EVI1, MLL2, and TET2/IDH are examples of nuclear epigenetic regulators that we suspect may be involved in the pathogenesis of melanoma and could be involved in enabling stem-like characteristics in select subpopulations." (PMID 26221190, 2015).
melanoma (continued). "We have also previously shown that restoration of the ‘5-hmC landscape’ via overexpression of TET2 in xenograft models resulted in more indolent, less invasive melanomas, suggesting an important, epigenetically-mediated tumor-suppressive role for TET2 activity and 5-hmC." (PMID 26462027, 2015). "In addition, we have identified that MECOM, a novel, central epigenetic regulatory gene, and TET2/IDH1, critical regulators of DNA demethylation, are frequently mutated in patient melanoma samples." (PMID 26221190, 2015). "It has been shown that overexpressing TET2 could partially reestablish a normal 5hmC profile in cultured melanoma cells and decrease their invasiveness in modeled animals." (PMID 25977731, 2015). "In addition, the decreased expressions of IDH2 and TET2 are responsible for the decreased 5 hmC and restoration of IDH2 or TET2 suppresses melanoma growth and increases tumor-free survival in animal models." (PMID 23671639, 2013). "Therefore, HIF-1a seems to regulate the expression of the TET2 enzyme, contributing to the modified epigenetic landscape of melanoma and it might represent a future target for melanoma therapies." (PMID 40427015, 2025). "To test this hypothesis, we expressed TET2 ectopically in melanoma cell lines." (PMID 39091741, 2024). "Indeed, in a melanoma setting removal of TET2 from myeloid cells reverted their immune suppressive phenotype induced by IL-1 and allowed a type 1 polarization leading to the recruitment of T cells that could contrast tumor growth." (PMID 35663987, 2022). "Although a recent work reported that TET2 augments the IFN-gamma-induced PD-L1 expression in melanoma, colon cancer, and acute monocytic leukemia cells, whether TET2 is involved in the epigenetic regulation of PD-L1 gene expression in breast cancer remains largely unknown." (PMID 34064441, 2021). "Indeed, mutation in TET2 is frequently found in hematopoietic malignancies, and the downregulation of TET proteins has been observed in several solid tumors, such as breast cancer, gastric, glioblastoma, liver, lung, melanoma and prostate." (PMID 34198989, 2021). "Moreover, it has been suggested that HIF1-α may interact with the TET2 protein in the melanoma and glioblastoma cell lines." (PMID 33352824, 2020). "During melanoma progression, the stimulation of their receptor (IL-1R) in M2-TAMs was found to up-regulate the expression of the DNA methylcytosine dioxygenase Ten-Eleven-Translocation-2 (Tet2), a well-known tumor suppressor exerting immunosuppressive functions in hematopoietic malignancies." (PMID 33212945, 2020). "In accordance, vitamin C was found to enhance TET2 activity and recruitment to promoter regions of chemokine, resulting in its increased expression in (B16-OVA) melanoma cells." (PMID 41210249, 2025). "Future research should also focus on exploring the therapeutic potential of modulating TET2 activity and its impact on PRAME expression, potentially leading to novel strategies for blocking melanoma initiation and progression." (PMID 39091741, 2024). "Examining RNA-seq datasets from The Cancer Genome Atlas (TCGA) and Genotype-Tissue Expression (GTEx) databases, we observed significant down regulation of TET2 and TET3 in melanomas (n=460) as compared to healthy skin samples (n=551)." (PMID 39091741, 2024). "Overall, based on the RNA-seq results for melanoma tumor tissues, we concluded that α-KG promotes IFNγ-STAT1/3-CD274 signaling through TET2/3, which in turn improves immune responsiveness and ultimately enhances the therapeutic efficacy of anti-PD1 therapy." (PMID 36854755, 2023). "The expression of TET enzymes, particularly of the three members TET1, TET2, and TET3, can vary between melanocytes and melanoma in different stages." (PMID 37834158, 2023). "DNA methylation-induced silencing of TET2 and TET3 resulted in an epithelial-to-mesenchymal-like process and promoted the metastasis of melanoma." (PMID 37834158, 2023).
melanoma (continued). "Together, these analyses verify that TET2/3-STAT1/3-CD274 signaling predicts a better immune microenvironment and better responsiveness to PD1 blockade in melanoma patients." (PMID 36854755, 2023). "We further found that TET2/3, STAT1/3 and CD274 were more highly expressed in anti-PD1-treated Yumm1.7-derived melanoma cells than in similarly treated B16F10 cells." (PMID 36854755, 2023). "In melanoma, ECM stiffness triggers translocation of Cdc42, a transcription factor belongs to Rho-GTPase, then upregulating ten-eleven translocation 2 (Tet2) expression which resulting in induction of quiescent via decreasing expression of p21 and p27." (PMID 36906534, 2023). "In melanoma cells, HIF-1α downregulation increases TET2 expression both considering the mRNA and protein levels." (PMID 33805247, 2021). "In melanoma, TGF-β1 determines the recruitment of DNMT3A to the TET2 gene locus, methylation of this gene, and subsequent silencing of TET2 expression, which induces an increase in the process of epithelial-mesenchymal transition." (PMID 33805247, 2021). "In contrast to DNMTs, the ten eleven translocation (TET) family of DNA demethylases (TET1, TET2, and TET3) are commonly downregulated in melanoma, and melanoma cells accordingly show reduced levels of 5hmC in their DNA compared with melanocytic nevi." (PMID 33024276, 2020). "The same study showed that 5hmC levels were also low in melanoma cells, and restoration of 5hmC by ectopic expression of IDH2 or TET2 suppressed melanoma growth and increased tumor-free survival in animal models." (PMID 33024276, 2020). "In the metastatic melanoma cell line, SK-MEL-1, 5-aza treatment up regulated TET2 and TET3 expression levels, which indicates that TET2 and TET3 are silenced through DNA methylation." (PMID 27852070, 2017). "As an effector, DNMT3A senses the TGF-β signal and silences TET2 and TET3 promoters to induce the EMT-like process and metastasis in melanoma." (PMID 27852070, 2017). "Taken together, our results indicate that TET2 and TET3 are suppressors of the EMT-like process in melanoma and that the silencing of these proteins by DNA methylation is one mechanism by which TGF-β induces an EMT-like process." (PMID 27852070, 2017). "Here, our results indicate that TET2 and TET3 are epigenetically silenced by DNMT3A-catalyzed DNA methylation in the TGF-β1-induced EMT-like process in melanoma." (PMID 27852070, 2017). "In summary, our in vitro experiments showed that TET2 and TET3 are suppressors of the EMT-like process in melanoma and DNMT3A-mediated epigenetic silencing is one mechanism by which TGF-β induces an EMT-like process." (PMID 27852070, 2017). "Here, we found that TET2 and TET3 play critical roles in the EMT-like process that occurs in melanoma." (PMID 27852070, 2017). "Here we report that DNA methylation induced silencing of TET2 and TET3 are responsible for the EMT-like process and the metastasis of melanoma." (PMID 27852070, 2017). "It will be interesting if, in the future, investigators dissect the signals that mediate the involvement of TET2 and TET3 in the regulation of the EMT-like process in melanoma." (PMID 27852070, 2017). "As an effector, DNMT3A senses the TGF-β signal and modifies TET2 and TET3 promoters to induce the EMT-like process and metastasis in melanoma." (PMID 27852070, 2017). "Moreover, overexpression of active TET2 in human melanoma cells suppressed tumor growth in NOD/SCID xenograft mice and improved tumor-free survival, which suggested that the decrease in TET2 could be one of the mechanisms leading to the loss of 5-hmC in melanoma." (PMID 27050164, 2016). "We first evaluated the expression level of TETs (TET1, TET2, and TET3) in primary cultured healthy human melanocyte lines (FOM-113) and various melanoma cell lines using qRT-PCR." (PMID 25977731, 2015).
melanoma (continued). "This is supported by the fact that restoring TET2 expression slows melanoma cell growth in mice xenografts and overexpression of IDH2 in a zebrafish model of melanoma improves tumor-free survival." (PMID 24202321, 2013). "In melanoma, down-regulation of TET, especially TET2, and IDH2 transcripts have been reported as mechanisms of 5-hmC loss." (PMID 24202321, 2013). "Moreover, the same authors demonstrated that TET2 enhances the expression of specific MHC class I antigen presentation genes, including TAP1 and TAPBP, in a murine melanoma cell line and other cancer cell lines." (PMID 40427015, 2025). "A cohort of primary melanoma samples from 14 patients were examined using cyclic immunofluorescence (CyCIF) imaging and antibodies against SOX10 (melanocytes), CK14 and panCK (epidermal keratinocytes), PRAME, TET2 and 5-hmC." (PMID 39091741, 2024). "Not surprisingly, abortion of TET2 in myeloid cells suppressed melanoma growth in vivo by shifting the immunosuppressive gene expression pattern in TAM to a proinflammatory one, thereby causing the downregulation of the immunosuppressive function." (PMID 37928272, 2023). "In summary, our findings confirmed that α-KG enhanced the immunotherapeutic efficacy of anti-PD1 through the TET2/3-STAT1/3-CD274 pathway and that supplementation with α-KG plus treatment with anti-PD1 might be a novel strategy for melanoma treatment." (PMID 36854755, 2023). "To elucidate how α-KG enhances the efficacy of anti-PD1 immunotherapy in melanoma, we conducted RNA sequencing of tumors treated with α-KG, anti-PD1 or α-KG + anti-PD1 and found that IFNG-STAT1/3-CD274 signaling and α-KG-dependent TET2/3 were significantly altered in the α-KG + anti-PD1 mAb group." (PMID 36854755, 2023). "Tet2 reshapes the chromatin accessibility of several key TFs at genomic binding regions, including BATF and ETS1 in CD8+tumor-infiltrating lymphocytes, thereby enhancing its anti-tumor immune function and suppressing melanoma growth in vivo." (PMID 36203205, 2022). "Mechanistically, they revealed that TET2 could be recruited by STAT1 to hydroxymethylate the PD-L1 gene promoter and enhance its transcription in murine melanoma and colon tumor upon IFN-gamma stimulation." (PMID 34064441, 2021). "Furthermore, CpG methylation-induced silencing of TET2 and TET3 induced EMT-like progression and metastasis in melanoma." (PMID 29849955, 2018). "In our experiments, overexpression of TET2 C-terminal partially suppressed the in vivo EMT-like process and the in vivo metastasis, yet it inhibited in vitro cell proliferation and the in vitro melanoma growth." (PMID 27852070, 2017). "TET2 and TET3 are silenced in melanoma cells by epigenetic mechanisms triggered by TGF-β and mediated by DNA methyltransferase 3A (DNMT3A); these events play a functional role in the epithelial-to-mesenchymal transition (EMT) and in metastatic processes of melanomas." (PMID 29156643, 2017). "We also studied human melanoma datasets from The Cancer Genome Atlas (TCGA), and found that the TET proteins, especially TET2 were downregulated, and the mesenchymal marker Vimentin and EMT master transcription factors like ZEB2, SNAIL2 and TWIST1 were up regulated." (PMID 27852070, 2017). "Most melanoma driver genes are not regulated by methylation, although it is hypothesized that TET2 has additional effects on other mechanisms such as genomic instability and DNA damage repair." (PMID 40116537, 2025). "Hence, these experiments emphasize that the epigenetic silencing of TET2 and TET3 critically contributes to the progression of melanoma and may help provide additional pertinent information for cancer diagnosis and treatment." (PMID 27852070, 2017). "In contrast, the inferred level of expression of TET1 was lower than TET2 and TET3 and did not change between melanoma and normal skin, suggesting a less important role in regulating global 5hmC levels." (PMID 39091741, 2024).
melanoma (continued). "Analysis of TCGA and GTEx databases confirmed a negative relationship between TET2 and PRAME mRNA expression in melanoma." (PMID 39091741, 2024). "Consistent with our above results, TET2/3, but not TET1, were downregulated in melanoma patients in multiple GEO datasets, and TET3 expression was positively correlated with STAT3 expression." (PMID 36854755, 2023).